LNCMB1 (lncRNA MYC regulated medulloblastoma associated 1)
Gene: Long non-coding RNA gene on chromosome 17 (32,141,226 to 32,143,135, reverse strand). Ensembl gene ENSG00000214708.
Diseases named in the same sentence as LNCMB1 in open-access papers:
LNCMB1 is named in the same sentence as 1 disease in open-access papers, as found by Europe PMC text mining. Sharing a sentence is not in itself a finding about the gene and the disease. The quoted sentences say what the papers report.
cancer (1 paper, 2021). A tumor composed of atypical neoplastic, often pleomorphic cells that invade other tissues. "With regard to lncMB1 it is a cytoplasmic transcript, antisense to Rhot1 gene, encoding for a RAS protein involved in mitochondrial homeostasis, apoptosis and cancer." (PMID 34359754, 2021). "Next, we addressed the function of lncMB2 and lncMB1. lncMB2 is a predominantly nuclear transcript, whose proximal genes ZNF703 and ADGRA2, mapping about 360 Kb and 460 Kb apart from lncMB2 locus (AC091182.1), respectively, are both related to cancer." (PMID 34359754, 2021).